SNORD3J (small nucleolar RNA, C/D box 3J)
Gene: Small nucleolar RNA gene on chromosome 10 (43,417,249 to 43,417,438, reverse strand). Ensembl gene ENSG00000221400.
Gene Ontology:
Biological process: RNA processing
Cellular component: nucleolus
Homologues: Orthologues: chimpanzee U3 (99% identical), macaque U3 (82% identical), dog U3 (69% identical). Paralogues in human: SNORD3P1 (78% identical), SNORD3D (77% identical), SNORD3E (76% identical), SNORD3G (75% identical), U3 (75% identical), U3 (74% identical), U3 (72% identical), U3 (71% identical), U3 (69% identical), U3 (68% identical), SNORD3H (68% identical), U3 (67% identical), and 8 more.